BRCA1 (BRCA1 DNA repair associated)
Diseases named in the same sentence as BRCA1 in open-access papers (continued):
Sharing a sentence is not in itself a finding about the gene and the disease.
breast cancer (continued). "The patients were divided into high-risk and low-risk groups for hereditary breast cancer based on the Korean National Health Insurance Service’s eligibility criteria for BRCA1/2 germline mutation testing." (PMID 38254240, 2024). "These factors include genetic predisposition, such as a family history of the disease, and mutations in genes like breast cancer susceptibility gene 1/2 (BRCA1/2)." (PMID 38941369, 2024). "This review article sheds light on the differences in tumour microenvironment between sporadic breast cancers and BRCA1 and, to a lesser extent, BRCA2 pathogenic variant (PV)-associated breast cancers, which are usually hereditary." (PMID 39682099, 2024). "Germline BRCA1/2 mutation carriers have a high incidence of breast cancer in their lifetime; the lifetime probability is approximately 57–65% for those with BRCA1 mutations and 45–49% for those with BRCA2 mutations." (PMID 38869771, 2024). "With regard to breast cancer risk after use of oral contraceptives in BRCA1/2-pV carriers, data are heterogeneous." (PMID 39259360, 2024). "The prevalence of BRCA1/2 mutations varies from 2.7% to 7.8% in women with breast cancer and from 2.9% and 13.5% in those with ovarian cancer." (PMID 38192174, 2024). "Recent molecular diagnostic studies have identified RECQL as an important breast cancer susceptibility gene, similar to BRCA1, BRCA2, and PALB2." (PMID 38439896, 2024). "All the investigations clearly show that, not only for breast cancer, BRCA1 and BRCA2 mutations stand out as the foremost high-penetrance genetic risk factors for ovarian cancer." (PMID 38391958, 2024). "Breast cancer survivors who carry a BRCA1 or BRCA2 gene mutation are at high risk of cancer recurrence." (PMID 39192282, 2024). "To identify alternative mechanisms of PARPi resistance, we generated orthotopic allografts using tumor cells derived from genetically engineered mouse models (GEMMs) of Brca1- or Bard1-deficient breast cancer." (PMID 38956205, 2024). "Is a postpartum diagnosis an independent risk factor associated with mortality among patients with young-onset breast cancer with germline BRCA1/2 pathogenic variants (PVs)?" (PMID 38639936, 2024). "Since the BRCA1 gene is a susceptibility gene for breast cancer, it can regulate the proliferation and differentiation of breast cells." (PMID 39156700, 2024). "For example, DNAJC1 and OLA1 (which interacts with BRCA1) have been linked to breast cancer in cancer GWAS studies." (PMID 39535534, 2024). "This is the first study of the effects of iodine on breast cancer risk in BRCA1 carriers, and the results should be validated in other populations." (PMID 38892720, 2024). "Strengthening our observations is a previous publication showing synthetic lethality of this combination in BRCA1-deficient breast cancer." (PMID 38519707, 2024). "The DNA damage repair phenotypes of cells expressing TMD-deficient TREX1 resemble those observed in breast cancer patients with inherited BRCA1/2 variants." (PMID 38824133, 2024). "Although a metaanalysis from 2013 did not produce a significant result, it did conclude that the influence of oral contraception on the risk of breast cancer in women with pV in BRCA1/2 genes is comparable to that in women in the general population." (PMID 39259360, 2024). "A previous study revealed that H. pylori infects gastric mucosal epithelial cells, and cytotoxin-associated gene A (CagA) antigen inhibits the function of DNA damage repair of the breast cancer susceptibility gene (BRCA1/2)." (PMID 39590127, 2024). "The surgical and (neo)adjuvant treatments of the patients carrying pathogenic germline BRCA1/2 mutation (gBRCAm) and early breast cancer." (PMID 39319938, 2024). "The effectiveness of surveillance in detecting breast cancer in BRCA1/2 mutation carriers was evaluated in 2017." (PMID 38791944, 2024).
breast cancer (continued). "BRCA1/2 genes are important biomarkers for assessing the risk of breast cancer, ovarian cancer, and other related cancers, significantly influencing the choice of individualized treatment for patients." (PMID 38167124, 2024). "A semi-annual surveillance scheme from age 25 to 30 years is offered to BRCA1/BRCA2 pathogenic sequence variants (PSVs) carriers for early detection of breast cancer (BC)." (PMID 38379091, 2024). "In this patient, a familial BRCA1 variant was found 15 years earlier at the time of a breast cancer diagnosis for his sister at the age of 35 (she developed a second breast cancer 15 years later, and pancreatic cancer at the age of 67)." (PMID 38929805, 2024). "The study found that 10% of breast cancer patients' cancer cells had BRCA1/2 gene mutations, and patients with BRCA1/2 gene mutations were more likely to suffer from breast cancer than normal people." (PMID 38886516, 2024). "This research investigates the effects of South Korea’s national insurance coverage (NIC) expansion and the inclusion of genetic counselors on BRCA1/2 mutation testing rates in breast cancer patients." (PMID 38791944, 2024). "The protein represented by 4KD7 plays a role in regulating the tumour-suppressor gene BRCA1 and mutations associated with an increased risk of breast cancer." (PMID 38399423, 2024). "11,847 BRCA1 variant carriers participated in global cohort research of the Breast Cancer Linkage Consortium that discovered a significant two- to three-fold increase in the risk of endometrial cancer." (PMID 38297203, 2024). "In 2009, the first clinical trial of the PARPi demonstrated a synthetic lethal for olaparib in breast cancer with BRCA1/BRCA2 deficiency." (PMID 37588193, 2024). "Results of this study suggest that among women with a BRCA1 sequence variation, MRI surveillance is associated with reduced breast cancer mortality risk." (PMID 38421676, 2024). "A limitation of this study is that model assumptions about the efficacy of breast cancer screening at young ages were mostly based on BRCA1/2 mutation carriers, who are known to have different breast cancer tumor characteristics than other women." (PMID 38635308, 2024). "The second most important factor associated with the incidence of breast cancer is the gene gent mutation of BRCA1 and BRCA2." (PMID 38473036, 2024). "Eight of the eleven patients were in the CDDP group and all were distant disease free, although one developed second primary breast cancer 9.77 years after surgery, who carried a BRCA1 mutation." (PMID 38123790, 2024). "The NCCN guidelines and the Korean Clinical Practice Guideline for breast cancer recommend annual mammography and breast MRIs for female BRCA1/2 mutation carriers." (PMID 39590130, 2024). "By inhibiting PARP, the damaged DNA cannot be effectively repaired, thus inducing the death of breast cancer cells with BRCA1/2 gene mutation." (PMID 38886516, 2024). "In the adjuvant setting, the OlympiA trial demonstrated improvements in overall survival (OS) after curative intent therapy in patients with germline pathogenic variants (gPVs) in BRCA1/2 in high-risk, early breast cancer." (PMID 38950525, 2024). "Women with germline BRCA1 or BRCA2 pathogenic variants (PV) account for 5% of all breast cancer (BC) and 15% of all OC." (PMID 39624976, 2024). "Homologous-recombination deficiency due to breast cancer 1/2 (BRCA1/2) mutations or mimicking BRCA1/2 mutations confer synthetic lethality with poly-(ADP)-ribose polymerase 1/2 inhibitors." (PMID 38657865, 2024).
breast cancer (continued). "The OlympiA trial found that 1 year of adjuvant olaparib therapy can improve distant disease-free survival and overall survival from early-stage breast cancer in patients with a germline BRCA1/2 mutation." (PMID 38170520, 2024). "For BRCA1 mutation carriers, an increase in breast cancer risk after ever use of OC was observed in the retrospective analyses, with HRs between 1.26 and 1.39." (PMID 38892081, 2024). "As for genetic factors, radiation-induced breast cancer is dependent on rat strain, and Brca1 haploinsufficiency renders rats susceptible to breast cancer induced by prepubertal radiation exposure." (PMID 39007844, 2024). "This economic evaluation estimates the cost-effectiveness of prevention strategies for ovarian and breast cancer among individuals with pathogenic variants in cancer susceptibility genes BRCA1, BRCA2, PALB2, RAD51C, RAD51D, and BRIP1." (PMID 38334999, 2024). "In this review article, we aim to provide an overview and update on the impact of HRT and HC on breast cancer risk in the general population compared to their effects on carriers of BRCA1/2 pathogenic variants." (PMID 38892081, 2024). "There is preliminary evidence suggesting that FCR is a major problem for breast cancer survivors carrying a BRCA1/2 mutation." (PMID 38192174, 2024). "An increased sensitivity toward cisplatin has also been observed in animal models with BRCA1-deficient mammary tumors." (PMID 38256203, 2024). "In a meta-analysis of 10 studies, there was a 57% risk for developing breast cancer before the age of 70 in women with BRCA1 pathogenic variants, and 49% in women with BRCA2 pathogenic variants." (PMID 38365640, 2024). "Little is known about the association between the loss of function of BRCA1/2 genes and the patterns of CNS involvement in breast cancer." (PMID 38365640, 2024). "The lifetime risk of breast cancer in BRCA1 carriers is approximately 70%, and the risk of ovarian cancer is approximately 40%." (PMID 38892720, 2024). "This cohort study describes the clinical outcomes of women with BRCA1/2 variant–associated breast cancer who were treated with breast-conserving therapy, including the risk of ipsilateral and contralateral cancer events and bilateral mastectomy-free survival." (PMID 38916888, 2024). "In a phase III clinical trial OlympiAD (NCT02000622) (Study Details Assessment of the Efficacy and Safety of Olaparib Monotherapy Versus Physicians Choice Chemotherapy in the Treatment of Metastatic Breast Cancer Patients With Germline BRCA1/2 Mutations." (PMID 38327984, 2024). "High-grade serous ovarian carcinoma (HGSOC) is the most prevalent histological subtype of epithelial ovarian cancer and is associated with mutations in the breast cancer susceptibility genes 1 and 2 (BRCA1 and BRCA2) in approximately 25% of cases." (PMID 39314634, 2024). "This review article aims to provide an overview and update on the effects of endocrine interventions on breast cancer risk in the general population in comparison to BRCA1/2 mutation carriers." (PMID 38892081, 2024). "The cumulative incidence risk of breast cancer by age 80 is reported to be 72% for BRCA1 mutation carriers and 69% for BRCA2 mutation carriers, while the cumulative incidence risk of ovarian cancer is 44% for BRCA1 and 17% for BRCA2." (PMID 39174799, 2024). "The mutation frequency in Chinese people is 9.45%, and approximately 20–40% of genetic breast cancer patients have BRCA1/2 germline mutations." (PMID 38439896, 2024). "Depending on the study, the lifetime risk of developing breast cancer in BRCA1/2 mutation carriers ranges from 45 to 80%, which is much higher than in the general population (13%)." (PMID 39192282, 2024). "Germline mutations (i.e., pathogenic or likely pathogenic variants) in BRCA1/2 (gBRCAm) affecting this vital DNA repair pathway predispose individuals to developing breast cancer by impairing homologous recombination and causing genomic instability." (PMID 39237557, 2024).
breast cancer (continued). "The approval of poly-ADP ribose polymerase (PARP) inhibitors for the treatment of BRCA1/2-mutated advanced ovarian cancers and more recently for BRCA1/2-mutated breast cancers illustrates the potential of SL-based therapeutics." (PMID 38478595, 2024). "LYN kinase is expressed in BRCA1 loss-of-function-dependent mouse mammary tumours, in the cells of origin of such tumours, and in human breast cancer." (PMID 38149669, 2024). "Due to the intricate interactions between ERα and BRCA1, it is essential to study the effect of these genes and their corresponding proteins, particularly when BRCA1 is mutated in breast cancer cells." (PMID 38398090, 2024). "A study on Springer spaniels revealed a significant association between the development of mammary tumours and BRCA1 and BRCA2 polymorphisms, with 97% of diagnosed cases possessing these alleles." (PMID 38573417, 2024). "Among BRCA1/2 mutation carriers, 55 (76.4%) of breast cancer patients experienced the onset of breast cancer before menopause, while 17 (23.6%) experienced it after menopause." (PMID 38167124, 2024). "According to a study conducted in Hong Kong and China, postmenopausal women and women with a BRCA1 mutation who consumed brewed coffee showed a decreased risk of breast cancer (AOR = 0.48, 95% CI = 1.10–2.03)." (PMID 39096427, 2024). "In conclusion, clinical data regarding the safety of concurrent olaparib and radiation therapy in patients with BRCA1/2-mutated breast cancer are very limited." (PMID 38799106, 2024). "We show that FLT1 is activated in the tumor cells of PARPi-resistant tumors from Brca1- and Bard1-deficient models as well as from breast cancer patients." (PMID 38956205, 2024). "Various studies have shown that the detection rate of BRCA1/2 gene mutations can be high in patients with bilateral breast cancer." (PMID 38167124, 2024). "Our study found that PALB2 variants, along with BRCA1/2 variants, were associated with increased breast cancer risk." (PMID 38270937, 2024). "The study group consisted of 45 women aged 35–76 years (average age 53 years), including 24 women with a confirmed diagnosis of breast cancer and BRCA1/2 germline mutation and 21 women diagnosed with invasive breast cancer and no BRCA1/2 germline mutations." (PMID 39080120, 2024). "Women who underwent RRSO had a lower risk of first diagnosis of breast cancer in BRCA1 mutation carriers; 20% vs 14% (HR= 0.63, 95% CI, 0.41-0.96) and BRCA2 mutation carriers; 23% vs 7% (HR= 0.36, 95% CI, 0.16-0.82)." (PMID 39507757, 2024). "PARP inhibitors have first obtained their indications in ovarian cancer and BRCA1/2-mutated breast cancer." (PMID 39334297, 2024). "The lifetime risk of developing breast cancer is increased to 40–80% in individuals who carry mutations in the BRCA1 and BRCA2 genes." (PMID 39096427, 2024). "The American Society of Clinical Oncology recommends testing for BRCA1/2 mutations to all patients newly diagnosed with breast cancer, who are of ≤65 years old." (PMID 38807767, 2024). "In a BRCA1-deficient breast cancer model, the concurrent use of the DNA repair enzyme PARP inhibitor and the STING agonist significantly amplified the anti-tumor effects of STING." (PMID 38523155, 2024). "Breast cancer and ovarian cancer pose a significant risk for BRCA1 carriers, with limited risk-reduction strategies." (PMID 38892720, 2024). "Only six patients underwent BRCA mutation testing, with one patient testing positive for BRCA1 mutation, but a family history of breast cancer was found in 6 (27.3%) cases." (PMID 38800480, 2024).
breast cancer (continued). "The high number of BRCA1 carriers in the population, coupled with the lifetime risk of ovarian and breast cancer, presents a need to identify additional factors that can reduce the risk." (PMID 38892720, 2024). "While BRCA1 mutation carriers typically develop basal-like breast cancers, breast cancers in BRCA2 mutation carriers are much more heterogenous." (PMID 38059556, 2024). "The analyses showed that the use of oral contraceptives in BRCA1/2-pV carriers initially led to an increased risk of breast cancer and in the long term to a reduced risk of ovarian and endometrial cancer." (PMID 39259360, 2024). "There is evidence that BRCA1/2-mutated tumors exhibit significantly increased CD8+ TILs, although in breast cancer, differential modulation between BRCA1 and BRCA2 mutations in the tumor immune microenvironment has been found." (PMID 39669575, 2024). "Only a few studies have previously focused specifically on gBRCAm in early-stage breast cancer or only on pathogenic variants of BRCA1/2." (PMID 39319938, 2024). "We have chosen to examine the phenotype of induced loss of Itga6 in Blg-Cre;Brca1F/F;Trp53F/F mice, a well-established model of basal-like tumors, mimicking features characteristic of human BRCA1-deficient breast cancer." (PMID 38835038, 2024). "For example, BRCA1 mutations are associated with longer survival in ovarian and endometrial cancers, but shorter survival in breast cancer." (PMID 38977680, 2024). "Compared with BRCA2 variant carriers (80 [46.5%]), women with BRCA1 variants (92 [53.5%]) were younger at breast cancer diagnosis and tended to have more advanced tumors, which were more likely to be hormone receptor negative and higher grade." (PMID 38916888, 2024). "Approximately 5% of patients diagnosed with breast cancer will have pathogenic or likely pathogenic germline variants in BRCA1 or BRCA2." (PMID 38950525, 2024). "Patients harboring gBRCAm are more likely to develop breast cancer at a younger age, with approximately 12% of the cases arising in women ≤40 years of age attributed to pathogenic or likely pathogenic variants in BRCA1 or BRCA214." (PMID 39237557, 2024). "For instance, a study showed that the cumulative incidence of local breast cancer recurrence in BRCA1/2 mutation carriers was 32% within 15 years after a breast‐conserving surgery (e.g., lumpectomy) and 9% after total mastectomy." (PMID 38192174, 2024). "For example, breast cancers in BRCA1 mutation carriers are typically high-grade, invasive ductal adenocarcinomas that fall into the triple-negative group (i.e., they lack estrogen and progesterone receptor expression and do not exhibit Her2 amplification)." (PMID 37832945, 2024). "In the presence of a BRCA1 mutation, the breast cancer phenotype is likely to be more aggressive, particularly with a TNBC profile, which is found in 10–20% of TNBC cases." (PMID 38543119, 2024). "The abnormal mutation of breast cancer susceptibility gene 1 or 2 (BRCA1/2) in breast cancer cells cannot repair DNA double-strand breaks but relies on the DNA single-strand repair pathway regulated by adenosine diphosphate ribose polymerase (PARP)." (PMID 38886516, 2024). "Approximately 50% of familial breast cancers harbor BRCA1 mutations, and a reduction in the levels of BRCA1 protein is also frequently observed in many sporadic breast cancers." (PMID 38734703, 2024). "A model construct for the BRCA1 Q1785X mutation associated with breast cancer contains a UAG premature stop codon followed by an R-ASO-sensitive context (+4C; +8G, +11G)." (PMID 39011883, 2024). "Heredity accounts for only 5–10% of breast cancer cases, with germline mutations in BRCA1 or BRCA2 accounting for 30% of inheritable breast cancer cases." (PMID 38672665, 2024).